APOE (apolipoprotein E)
Diseases named in the same sentence as APOE in open-access papers (continued):
Sharing a sentence is not in itself a finding about the gene and the disease.
cardiovascular disease (continued). "Apolipoproteins have been demonstrated to play physiological roles on nutrition transport and energy metabolism, and numerous variants have been revealed in some apolipoproteins including ApoA1, ApoA5, ApoB, ApoC3 and ApoE, which are associated with the risk of cardiovascular disease." (PMID 21799896, 2011). "Likewise, genes involved with a higher risk of cardiovascular disease, such as the isoform ApoE4 of ApoE (Apolipoprotein E), are more prevalent in Ps patients." (PMID 21299865, 2011). "APOE, one of the most studied genes in risk assessment of cardiovascular disease, plays a key role in the metabolism of cholesterol and triglycerides by binding to receptors on the liver and helping to mediate the clearance of chylomicrons and very low-density lipoproteins from the bloodstream." (PMID 20406466, 2010). "Therefore, APOE ε4 is a strong genetic risk factor for cardiovascular disease." (PMID 36421848, 2022). "Studies with diesel exhaust particles in high-fat fed ApoE deficient mice have also demonstrated the value of this susceptibility model over wildtype mice to support the epidemiological evidence that links exposure to airborne particles to cardiovascular disease." (PMID 32422323, 2020). "Thus, deficiency in ApoE not only results in increased susceptibility to chronic lung inflammation, but also could lead to increased susceptibility to cardiovascular diseases." (PMID 33022979, 2020). "The allelic variants of ApoE are associated with increasing cholesterol and lipid profile in the range E4 > E3 > E2 so that E4 carriers have higher lipoprotein fractions and associated increased risk of cardiovascular disease, dementia and stroke, compared to E2 carriers." (PMID 25773008, 2015). "To overcome these caveats, we studied a large cohort of 4,660 Spanish middle-aged men free of Cardiovascular Disease to investigate whether APOE-SNPs, rs429358 and rs7412, are associated with body fatness measures, body mass index and waist girth, over and above the effect on plasma lipids." (PMID 25268647, 2014). "We also investigated whether APOE was associated with cardiovascular disease in RA patients." (PMID 23613766, 2013). "Here, KMUP-1 showed the ability to alleviate HFD-enhanced cardiovascular diseases through anti-inflammation and antiapoptotic effects, restoration of impaired autophagy in the aorta, and normalization of lipid metabolism in ApoE-KO mice." (PMID 41194853, 2025). "While APOE is most extensively studied in the context of AD, its broader involvement in other neurological and cardiovascular disorders further underscores its relevance in precision medicine." (PMID 40943807, 2025). "Accordingly, several reports have indicated that APOE ε4 carriers have increased odds for cardiovascular diseases." (PMID 41035826, 2025). "With the advancement of research in the field of inflammation, a number of novel biomarkers—such as sirtuins, miRNAs, ST2, ApoE, and adiponectin—have also been proposed for use in the diagnosis and prognostic evaluation of cardiovascular diseases." (PMID 41007677, 2025). "ApoE mimetic peptides bind to LRPs and play a significant role in reducing inflammation and preventing cardiovascular diseases as well as neurodegenerative diseases." (PMID 39872504, 2024). "Results remained similar after adjusting for cardiovascular disease or apolipoprotein E ɛ4 carrier status." (PMID 38829458, 2024). "Results remained similar after further adjustment for APOE ɛ4 status or prevalence of cardiovascular disease at metabolomics assessment, while adjustment for APOE ɛ4 status attenuated some associations more than adjustment for cardiovascular disease." (PMID 38829458, 2024).
cardiovascular disease (continued). "Peripheral APOE plays a critical role in regulating lipid metabolism and has profound implications for cardiovascular disease (CVD) function and systemic inflammation." (PMID 38903305, 2024). "In a study by Sarduet al., sirtuins, microRNAs, suppression of tumorigenicity 2 (ST2) protein, apolipoprotein E protein,and adiponectin emerged as promising biomarkers for the diagnosis and prognosisof cardiovascular disease (CVD)." (PMID 39076342, 2024). "A total of 144 participants aged from 18 to 24 underwent 3T MRI and genotyping for APOE and MAPT to investigate unique impacts of these genetic risk factors in a cohort without significant comorbid conditions such as metabolic and cardiovascular diseases." (PMID 37693814, 2023). "ApoE function is widely studied in blood, liver and peripheral systems related to cardiovascular disease." (PMID 37947642, 2023). "The anti-inflammatory potential of ApoE mimetics has been evaluated, primarily in neurological and cardiovascular disease settings." (PMID 37242746, 2023). "ApoE is a multifunctional regulator protein for integrating signaling of neuron plasticity, cognition, and inflammation-related cardiovascular disease and fat metabolism." (PMID 38062308, 2023). "When fed with an HFD or a high-cholesterol diet, ApoE-knockout mice can develop atherosclerotic lesions; several features of cardiovascular disease are similar between these mice and humans." (PMID 37764856, 2023). "The polymorphic protein apolipoprotein E (APOE), central to lipid transport and metabolism, is well-recognized for the role of its isoforms as important predictors for human cardiovascular disorders and neurodegenerative diseases." (PMID 37010884, 2023). "In summary, ε2/ε2 genotypes are less represented in our population, whilst our study has shown that carrying ApoE*ε4 presents with higher serum levels of TC, TG and LDL-C and a higher 10-year risk of cardiovascular disease." (PMID 37134097, 2023). "Some risk factors for AD have been found to be family medical history, elderliness, the apolipoprotein E (APOE) ε4 allele genotype, cardiovascular disease risk factors, way of living, and psychosocial factors." (PMID 35049930, 2022). "HDL containing apoE generally protects against cardiovascular risk, but apoC-III in HDL negates the beneficial effect of apoE on HDL metabolism and relation to cardiovascular disease." (PMID 35371605, 2022). "Increased ApoE concentrations have generally been shown to be related to increased levels of triglycerides and cholesterol, which are well known drivers of cardiovascular diseases." (PMID 36380282, 2022). "The APOE ε4 (APOE4) allele is a major genetic risk factor for Alzheimer’s and cardiovascular diseases." (PMID 35915083, 2022). "The Apolipoprotein E (APOE) gene polymorphism (rs429358 and rs7412) shows a well-established association with lipid profiles, but its effect on cardiovascular disease is still conflicting." (PMID 35332187, 2022). "Previous studies have shown that apolipoprotein E knocked out mice will be more likely to developed cardiovascular disease after circadian rhythm was interrupted." (PMID 35484552, 2022). "Other mutations in APOE, such as L28P in an APOE4 backbone (APOE4-Freiburg) or APOE3-R145C (APOE3-Philladelphia) have been linked to increase risk for lipid disorders and cardiovascular diseases." (PMID 36348357, 2022). "The association between the APOE genotype polymorphisms and the risk of suffering T2DM and cardiovascular disease have also been reported, pointing at APOE4 as a risk factor for T2DM and cardiovascular diseases." (PMID 36153580, 2022). "The results show that, despite efforts and new technologies, only two genes, APOE and FOXO3A, involved in the protection of cardiovascular diseases, have been shown to be associated with longevity in nearly all studies." (PMID 35628444, 2022).
cardiovascular disease (continued). "Our network analyses suggest direct relationships between ε4 status and metabolic risk factors in women, such as waist circumference and systolic blood pressure, supporting previous research on the role of ApoE in females with cardiovascular disease." (PMID 34267647, 2021). "The dysregulation of the APOE expression and genetic variance of the APOE influence the APOE functions and lead to the pathogenesis of nervous and cardiovascular diseases eventually." (PMID 33490286, 2021). "Pinocembrin, a flavonoid from propolis, is shown to affect cardiovascular diseases based on its ability to regulate apolipoprotein E (ApoE; a protein involved in the metabolism of fats) and reduce rho kinase (regulates shape and movement of cells)." (PMID 34444688, 2021). "Among all three APOE isoforms, APOE2 and APOE3 are preferentially associated with HDL while APOE4 with LDL and VLDL, lipoproteins that are strongly associated with cardiovascular diseases and AD." (PMID 32899606, 2020). "In order to better resemble the human cardiovascular disease and to speed up plaque progression, we treated ApoE-KO mice with aldosterone at a dose of 6 μg/kg/day." (PMID 32231663, 2020). "The APOE-ε4 variant elevates serum LDL and homocysteine concentrations, thereby increasing the risk of cardiovascular diseases." (PMID 32727492, 2020). "In a recent meta-analysis examining longevity genetic polymorphisms, all significant genes (APOE, FOXO3A, ACE, Klotho and IL6) play roles in cardiovascular pathways, such as lipid metabolism, or have been previously linked to cardiovascular disease." (PMID 30889929, 2019). "ApoE KO mice fed with high-fat diet have been widely used to study the pathogenesis of cardiovascular disease." (PMID 31575906, 2019). "Pinocembrin, in particular, is thought to influence cardiovascular diseases based on its ability to regulate ApoE and reduce rho kinase." (PMID 31717277, 2019). "apoE was initially recognized for its importance in lipoprotein metabolism and cardiovascular disease." (PMID 29999587, 2019). "The APOE-ɛ4 allele has been shown to increase the risk of AD and cardiovascular disease but to be protective for AMD, while the converse appears to be true for the APOE-ɛ2 allele." (PMID 31568508, 2019). "Human Apolipoprotein E (APOE) gene that is located on chromosome 19 is involved in lipid homeostasis and is implicated in cardiovascular disease." (PMID 28487499, 2017). "The genes ADIPOQ, ACE2, APOE and CETP are implicated in these processes and polymorphism in these genes have been reported responsible to cause cardiovascular diseases (CVD) in diabetic patients." (PMID 28761062, 2017). "Background and Objective: Apolipoprotein E (APOE) plays important roles in lipoprotein metabolism and cardiovascular disease." (PMID 29311965, 2017). "APOE is a class of plasma apolipoprotein totaling 299 amino acids, and it is involved in lipoprotein metabolism and the development of cardiovascular diseases." (PMID 29311965, 2017). "Carriage of ε2 is associated with higher circulating concentrations of ApoE, lower circulating concentrations of low-density lipoprotein cholesterol (LDL-C), and a lower risk of cardiovascular disease (CVD) events." (PMID 27755538, 2016). "ApoE concentrations in individuals who later developed cardiovascular disease by case/control status in all three studies." (PMID 27755538, 2016). "The present study utilized apolipoprotein E knockout mice with 5/6 nephrectomy as a model of combined kidney disease and cardiovascular disease to investigate the effect of exercise on aortic plaque formation, vascular function and systemic inflammation." (PMID 25799529, 2015). "With regard to ApoE, ApoE4 genotype is associated with increased morbidity and mortality, and represents a significant risk factor for CVD cardiovascular disease and late-onset AD." (PMID 26404241, 2015).
cardiovascular disease (continued). "Furthermore, it appears that chronic systemic inflammation may provide a common underlying link connecting many AD risk factors (i.e., APOE genotype, cardiovascular disease, T2DM, poor diet, poor sleep quality, and a sedentary lifestyle)—all of which may be considered proinflammatory factors." (PMID 25538616, 2014). "In the Tunisian population the APOE E4 appears to be only indirectly involved in the severity of cardiovascular disease." (PMID 24571688, 2014). "We analyzed fasting plasma lipids and genotyped the two main APOE-SNPs (rs429358 and rs7412), both located in the fourth exon of the APOE, in 4660 Caucasian middle-aged men free of cardiovascular disease." (PMID 25268647, 2014). "ApoE knock-out mice were widely used in cardiovascular disease research as a classical animal model." (PMID 24526524, 2014). "ApoE is responsible for catabolism of triglyceride-rich lipoprotein and cardiovascular diseases and was found to be related to proinflammatory cytokines." (PMID 24194784, 2013). "Further evidence for the theory that increased HMGCoA reductase leads to increased NADPH oxidase activity and cardiovascular disease comes from studies on people with mutant forms of ApoE." (PMID 23122424, 2012). "Human apolipoprotein E (apoE) is one of the most frequently studied proteins known to be involved in lipid metabolism and cardiovascular disorders." (PMID 21253017, 2011). "Over the past few decades, the availability of new investigative tools, including the homozygous apolipoprotein E knockout (ApoE KO) mouse, has contributed to understanding the atherosclerotic process and cardiovascular diseases." (PMID 20723257, 2010). "This same locus has been associated with apolipoprotein E levels, LDL cholesterol levels, inflammatory traits, and cardiovascular-disease outcomes." (PMID 20442857, 2010). "While many associations are not consistently noted from study to study, a review of the available studies reveals a modest overall association of clinical cardiovascular disease or SCA with variants in candidate genes, such as APOE, ACE, and NOS3." (PMID 17903303, 2007). "In order to gain a more comprehensive understanding of the aetiology of apolipoprotein E4 genotype-cardiovascular disease (CVD) associations, the impact of the apoE genotype on the macrophage inflammatory response was examined." (PMID 17416347, 2007). "Notably, genetic variants in APOE have been consistently associated with LDL levels and predisposition to cardiovascular disease." (PMID 40630117, 2025). "Thus, the association between APOE ε4 and CVD risk highlights the importance of genetic screening, particularly in populations with a family history of cardiovascular disorders." (PMID 40671162, 2025). "To investigate the effect of APOL1 genotype in cardiovascular diseases, we established and characterized a mouse model, by crossing ApoE knock-out mice and BAC/APOL1 mice carrying the APOL1-G0 or APOL1-G1 variant controlled by the human APOL1 gene locus promotor." (PMID 39803526, 2024). "However, studies examining the association between ApoE in HDL and cardiovascular disease outcomes have been inconclusive." (PMID 37242746, 2023). "Therefore, the ApoE−/− mouse model is frequently used for lipid metabolism and cardiovascular disease research." (PMID 37091976, 2023). "ApoE abnormality is a well-known risk factor for cardiovascular disease, and rats lacking ApoE showed cardiac dysfunction after high-fat diet." (PMID 35433888, 2022). "The ApoE genotype has implications for cardiovascular diseases and neurodegenerative disorders." (PMID 36380282, 2022). "The observed upregulation of APOE mRNA in young DSS rats in comparison to SD rats may be explained by the activation of adaptation to the developing cardiovascular disorder in the DSS rats." (PMID 35562955, 2022). "Other important risk factors of progression to AD, such as APOE genotypes and cardiovascular disease, were not considered for survival analyses." (PMID 36688162, 2022).
cardiovascular disease (continued). "The ApoE−/− mouse is a well-established model of cardiovascular disease, in which a diet rich in fat and cholesterol on an ApoE deficient background accelerates the development of hypercholesteremia, atherosclerotic plaques and inflammation of the skin and other tissues." (PMID 36685213, 2022). "APOE gene variation has been associated with the concentration of C-reactive protein (CRP), a well-established marker of inflammation and an independent risk factor for cardiovascular disease (CVD)." (PMID 36361733, 2022). "Since the common polymorphisms of ApoE can significantly affect the variability of lipid metabolism, LSR may be involved in the pathology of type III hyperlipidemia and cardiovascular disease." (PMID 33763152, 2021). "In addition, significant associations were found between ApoE haplotypes (TCG) and cardiovascular disease in patients and healthy controls with (P-value <0.01)." (PMID 33437219, 2021). "However, the exact interference between Cyclophilin A and apoE in cardiovascular diseases requires further investigation." (PMID 34575848, 2021). "Research showed that high plasma levels of apolipoprotein E (APOE), a protein involved in lipid transport and metabolism, are associated with increased risk of cardiovascular disease and may serve as a marker of human aging." (PMID 32602849, 2020). "In Han Chinese (784 with cardiovascular diseases and 730 without cardiovascular diseases) APOE rs7259620 had a positive association with cardiovascular diseases only in men, not women without adjusting for the covariates." (PMID 32727492, 2020). "Interestingly, the multiallelic apolipoprotein E gene (APOE), an important regulator of cholesterol homeostasis, has been similarly linked to Alzheimer's disease and cardiovascular disease." (PMID 33042114, 2020). "APOE genotype was associated with baseline lipid fractions (e.g. mean difference(95%CI) in LDL(mg/dL) for ε2 versus ε33: -17.1(-18.1–16.0), and ε4 versus ε33: +5.7(4.8;6.5)), but the association between APOE and mortality was unaltered after adjustment for baseline LDL or cardiovascular disease." (PMID 31356640, 2019). "Furthermore, APOE, a protective protein for cardiovascular diseases, can interact with PPARγ to decrease cardiovascular disease risk." (PMID 31534622, 2019). "The ABCG1 gene encodes the ABCG1 protein that is essential for the regulation of lipid metabolism and influences blood lipid levels, and the APOE gene is considered a candidate gene for cardiovascular disease because the APOE protein influences total serum cholesterol levels in different ways." (PMID 31823830, 2019). "Epigenetic modification of ABCG1 and APOE may play a key role in the pathway from disturbed blood lipid levels to the development of cardiovascular diseases." (PMID 31823830, 2019). "Further, we propose a novel mechanism of regulation of the activation and receptor recognition of apoE that could prove valuable to interpret its role in Alzheimer and apoE-related cardiovascular diseases." (PMID 29933361, 2018). "Since its identification in 1973, ApoE has become one of the most widely studied gene variants, not only for cardiovascular disorders but also in relation to several other medical conditions such as neurodegenerative and autoimmune diseases." (PMID 25071563, 2014). "Plaque progression in APOE −/− mice has been used as an animal model of cardiovascular disease." (PMID 23894396, 2013). "Interestingly, whereas ApoE is likely to impact cardiovascular diseases due to an alteration of the circulating lipidic profile, its role in cancer seems to be independent of this association." (PMID 23372804, 2013).